CD4 (CD4 molecule)
Diseases named in the same sentence as CD4 in open-access papers (continued):
Sharing a sentence is not in itself a finding about the gene and the disease.
COVID-19 (continued). "In our study, we observed reduced CD4+ T cell responses against the JN.1 subvariant compared with the ancestral strain, specifically in the COVID-19-naïve group." (PMID 39772110, 2024). "The major infectious waste generating areas were the CD4, molecular, and tuberculosis and COVID-19 areas." (PMID 39823086, 2024). "In conclusion, people with PCC showed a skewed polarization of CD4+ Th subsets with altered functionality that was more similar to individuals with severe and critical presentations of acute COVID-19 than to people who fully recovered from mild disease." (PMID 39257580, 2024). "Since CD4 and CD68 are usually present on the macrophage surface, macrophages appear to be the driving force of COVID-19-associated inflammation, especially if trophoblast necrosis is present." (PMID 39057113, 2024). "Our findings revealed a causal impact of CD4+ TEM cell markers on the risk of PTB and COVID-19, providing evidence identifying two markers (GBP2 and LAG3) as prospective targets for the prevention of PTB and COVID-19 infection." (PMID 39337460, 2024). "We identified distinct CD4+ T cell responses between COVID-19 and influenza infection, with an increase in Tnaive cells in COVID-19 and Temra cells in flu." (PMID 38359792, 2024). "The analysis found that whilst the frequencies of CD4 + T cells were reduced on Day 211 compared to Day 36, for some participants they remained higher compared to baseline, placebo-controlled, and COVID-19 pre-pandemic samples." (PMID 38675770, 2024). "The decrease in CD4 + T cell levels after COVID-19 onset was greater in patients with moderate-to-severe disease than in those with mild disease." (PMID 38172680, 2024). "The presence of HLA-positive CD4 lymphocytes indicates prolonged circulation in the bloodstream, suggesting an activated state of cells even post-COVID-19." (PMID 38468605, 2024). "Multiple studies have documented a substantial decline in CD4+ T cell count as the severity of COVID-19 progresses." (PMID 39654887, 2024). "In some studies, a low CD4 count (< 200 cells/mm3) appeared to be a critical contributing factor to adverse COVID-19 outcomes, outweighing viral suppression as a significant contributor." (PMID 37821620, 2024). "ASyS patients with severe COVID-19 had significantly reduced peripheral CD4+ T cells, lower CD4/CD8 ratio, and fewer naive B cells but more class-switched memory B cells compared with controls." (PMID 38500883, 2024). "In COVID-19 naïve participants, the key phenotypic responses of vaccination on CD4+ T cells included CD4+ T cell activation, expansion of circulating CD4+ memory subsets, and increase in Treg memory subsets." (PMID 39340069, 2024). "Titers of COVID-19 antibodies were lower for patients with CD4 cell counts of less than 200 cells/μL in the first, second, and third serological tests with statistical significance; p = 0.0001 for the first titer." (PMID 39772116, 2024). "Both CD9 and CD63 are involved in exosome formation, and COVID-19 plasma exosomes stimulate pro-inflammatory responses that affect CD4/CD8 T cells, and CD14+ monocytes." (PMID 39712003, 2024). "Immune cell infiltration showed that patients with COVID-19 had significantly higher levels of plasma cells, resting memory CD4 rest cells, monocytes, M0 macrophages, resting mast cells, and neutrophils than the healthy population." (PMID 38455049, 2024). "In this study, flow cytometry results showed that the CD4+T cell count in toxoplasmosis-infected COVID-19 patients was partially lower (430–450 cells/mm3) than in healthy subjects (500–1500 cells/mm3)." (PMID 38172676, 2024). "In this prospective, longitudinal, observational study, we analyzed the changes produced in both humoral and cellular immune responses in PWH with normal CD4/CD8 ratio in response to the full vaccination schedule against COVID-19." (PMID 38812512, 2024).
COVID-19 (continued). "Conversely, among patients with acute COVID-19, only 20% (n = 2) with elevated CD4+ T cell levels experienced normalization during follow-up, while 70% (n = 7) maintained elevated levels at follow-up." (PMID 39044945, 2024). "It was proposed that the reactivation of latent tuberculosis in post-SARS-CoV-2-infected patients occurs because CD4+ T cells are exhausted and reduced in COVID-19 patients." (PMID 40729284, 2024). "PLWH hospitalized with COVID-19 had higher percentages of CD4+ CM PD-1+, CD8+, and CD8+ EM4 T-cells co-expressing CD57 and PD-1, and lower percentages of the CD8+ EM subset." (PMID 39597537, 2024). "The association between Primary cutaneous CD4 small/medium T-cell lymphoproliferative disorder (PCSM-TCLPD) and COVID-19 immunization has been sparsely documented in the medical literature." (PMID 38541710, 2024). "We highlight two distinctive populations: one encompassing PWH with COVID-19, characterised by CD4 + counts over 350 cells/mm3, a high prevalence (92%) of VS and a mortality rate of 12%." (PMID 38789972, 2024). "Nevertheless, several authors have shown that IFN-γ by CD4+ T cells numerically dominated over IFN- γ by CD8+ T cells after COVID-19 immunization, similar to what was found in our study for individuals vaccinated with 2 doses of PZ and previous infection." (PMID 38572317, 2024). "The findings highlight the potential of CD4+ T cell as a novel predictive tool for COVID-19 patients treated with azvudine." (PMID 39654887, 2024). "CD4 Th10 cells have been shown to be equally effective in inducing differentiation in B cells as Tfh cells and have been identified in response to COVID-19 vaccines." (PMID 38791389, 2024). "CVnCoV-induced CD4+ T cell responses specific to the SARS-CoV-2 spike antigen were comparable to those of COVID-19 convalescent patient samples." (PMID 38675770, 2024). "The number of CD4+ T cells significantly increased in individuals with mild-to-moderate COVID-19 who were administered 150 mg of demeclocycline on a daily basis." (PMID 37612352, 2023). "T cell depletion has been observed in COVID-19 patients, with a progressive reduction in CD4 and CD8 T cells in those with severe infection as compared with mild COVID-19 disease." (PMID 38041026, 2023). "Children with COVID-19 also exhibited higher frequencies of CD4+ and CD8+ T cells expressing cytokines at baseline and upon SARS-CoV-2 antigen–specific stimulation in comparison to children with other infections." (PMID 38116577, 2023). "Studies using peptides encompassing S511–530 have identified the region to contain a potential CD4+ T cell epitope in cohorts of individuals recovered from COVID-19 (3%–22% of individuals responded)." (PMID 37471227, 2023). "It has been shown that COVID-19 vaccines can substantially boost spike-specific CD4+ T cell responses, and have a modest effect boosting spike-specific CD8+ T cells, in previously infected individuals after immunization." (PMID 36776863, 2023). "We demonstrate that the tetravalent S1 subunit protein COVID-19 vaccine candidate induces CD4+ and CD8+ T cell activation, as indicated by increased expression of CD69, HLA-DR, CD38, and Ki-67 activation and proliferation markers on both T cell subsets." (PMID 37830800, 2023). "We also found activated CD4+ T and NK T (natural killer T) cell populations to be elevated, compared to other cell types, in COVID-19-positive individuals." (PMID 37886355, 2023). "The total ssGSEA score (the sum of absolute scores across 22 leukocyte components) was remarkably higher in the samples with COVID-19 than those in the azoospermia, including activated CD4 T cells, activated CD8 T cells, macrophages, and T helper cells." (PMID 37283758, 2023). "SEACells identified COVID-19-enriched CD4+ T cell states that are removed by typical batch correction and undetected at the single-cell level." (PMID 36973557, 2023).
COVID-19 (continued). "It was observed that SARS-CoV-2 infection exhibited a high degree of heterogeneity within all the three arms of the adaptive immune response, including memory B cells, CD8+ T cells and CD4+ T cells amongst more than 90% of COVID-19 patients." (PMID 37091818, 2023). "It has previously been shown that convalescent COVID-19 patients harbor an efficient CD4+ T cell response against the SARS-CoV-2 spike (S) glycoprotein." (PMID 37153606, 2023). "Most studies of COVID-19 in PWH have associated lower current CD4 with worse outcomes; nadir CD4 has seldom been assessed." (PMID 36805331, 2023). "Prior reports on COVID-19 showed lower frequencies of overall CD4+ and CD8+ T lymphocytes in BALF samples compared to the peripheral blood." (PMID 36986364, 2023). "DN3 B cells have been identified as extrafollicular B cells in several immune conditions including IgG4-related disease and COVID-19; these conditions are accompanied by CD4+ CTL enlargement." (PMID 38077321, 2023). "One patient had started antiretroviral treatment 63 days before the first positive swab but presented a low CD4+ count at COVID-19 diagnosis (CD4+ 20 cells/μL)." (PMID 37760757, 2023). "Preliminary findings also suggest that lower CD4 and HIV viremia are associated with worse outcomes after COVID-19 in PWH." (PMID 36805331, 2023). "The present study evaluated CD4+ T cell responses from six mRNA-vaccinated subjects and six COVID-19-infected subjects." (PMID 37790414, 2023). "We found that Foralumab-treated subjects greatly recover from naïve CD4+ reduction observed at day -2 in COVID-19-infected subjects." (PMID 36881624, 2023). "Of note, in more severe and critically COVID-19 patients, counts of peripheral CD4+ and CD8+ T cells are reduced, while their status is hyperactivated." (PMID 36757971, 2023). "Participants with a baseline CD4 count > 350 had greater protection from COVID-19, at 53.4% (95% CI: 19.6–75.3) p = 0.004." (PMID 38005865, 2023). "The inhibitory effect of the NSP7-289 on CD4+ T cell proliferation was also tested using PBMCs collected from COVID-19 convalescent donors." (PMID 38124752, 2023). "The representative hierarchical cluster shows the distinction of MIS-C from the COVID-19 group and other infections group in both CD4+ and CD8+ T cells." (PMID 38116577, 2023). "The results showed that the proportion of monocytes, T cells CD4 memory activated, and Mast cells resting was significantly increased in COVID-19 patients with Omicron infection, while T cells CD4 memory resting was significantly decreased." (PMID 37630661, 2023). "The CD4+ T cell population phenotypes in convalescent COVID-19 patients are predominantly central memory phenotype (CD45RO+, CCR7+), followed by an effector memory phenotype (CD45RO+, CCR7-)." (PMID 37091818, 2023). "Substantial drop in total T cell, CD8 or CD4 T cell counts, especially in the sickest COVID-19 patients." (PMID 37426635, 2023). "Reductions in the CD4+ and CD8+ αβ T cell numbers and decreased IFN-γ production by αβ T cells have also been linked to the disease severity observed in COVID-19 patients." (PMID 37111440, 2023). "Understanding the humoral immune response induced by the inactivated COVID-19 vaccine and the impact of CD4 cell count on vaccine response in PLWH were essential in decision-making regarding future disease control and revaccination strategies." (PMID 36670363, 2023). "In the younger group, CD4 SIPhigh level predicted serological responses induced by COVID-19 vaccination ((3/12 25.0%) vs 25/42 (59.5%), p=0.035) compared to patients with CD4 SIPlow." (PMID 37334387, 2023). "It is worth noting that immunologic memory of COVID-19-specific antibodies, CD4+ T cells, CD8+ T cells, and memory B-cells, lasts between five to eight months based on cell lineage." (PMID 38164412, 2023). "In patients with COVID-19, not only were the CD4 and CD8 cells low, but they had increased pro-inflammatory cytokines." (PMID 36839456, 2023).
COVID-19 (continued). "Amongst COVID-19 patients increasing disease severity correlated with a decrease in CD4 and CD8 positive lymphocytes." (PMID 36635274, 2023). "The decreased CD4+ T cell level is even used as an independent predictor for in-hospital death in COVID-19 patients." (PMID 37762093, 2023). "As we mentioned, the roles of CD4+ CTLs have also been described in various inflammatory and fibrotic diseases, i.e., IgG4-related disease, severe COVID-19, and systemic sclerosis." (PMID 36580373, 2023). "The increase of DP T cells with CD3+CD4+CD8+ immunophenotype among mononuclear WBCs in the process of recovery from COVID-19 was revealed." (PMID 37034572, 2023). "Meanwhile, BHB treatment resulted in improved mitochondrial functionality for fatty acid and amino acid oxidation while leading to reduced glycolysis in CD4+ lymphocytes in patients with severe COVID-19." (PMID 37376562, 2023). "All T cell subsets were significantly decreased in non-survivors, but a global reduction in the absolute number of CD4+ T cells is common among COVID-19 patients (especially those with severe manifestations) with different molecular and cytokine profiles." (PMID 37240926, 2023). "Compared to patients with Kawasaki syndrome, patients with SLE and COVID-19 tended to have an increased proportion of LCs, with an enrichment in conventional CD4+ or CD8+ T cells and NK cells and, to a lesser extent, in γδ T cells." (PMID 37285432, 2023). "These first provide a resource of model-characterized HLA-II epitopes for tracking CD4+ T cells in COVID-19." (PMID 37471227, 2023). "Our results revealed that memory B cells, CD8+ T cells, and CD4+ memory resting T cells were reduced in COVID-19, while plasma cells, CD4+ memory activated T cells, and neutrophils were increased when compared to healthy controls." (PMID 37822934, 2023). "CD4+ T cells from severe COVID-19 patients had decreased expression of IFNγ and IL-17A in relation to cells from patients with the moderate form of the disease or healthy donors." (PMID 37523305, 2023). "High immunosuppression regiment leads to an impaired humoral immune response and CD8 T response to two doses of COVID-19 vaccine, anyway the ability to generate clones of CD4 T lymphocytes specific for SARS-CoV-2 spike proteins is preserved." (PMID 37316832, 2023). "Activated CD4+ T and NK T cells were the most abundant cell types compared with other cell types in the COVID-19 patients." (PMID 37886355, 2023). "Of note, while severe courses of COVID-19 correlate with high levels of SARS-CoV-2-specific antibodies during and after disease, an early generation of strong virus-specific CD4+ and CD8+ T cell responses is associated with milder symptoms." (PMID 36839516, 2023). "Nevertheless, when we applied both TCA and Seurat to the longitudinal scRNA-seq data of activated CD4+ T cells of a COVID-19 patient, the two methods generated rather different results on up- or down-regulated genes." (PMID 36973282, 2023). "Recent studies, including more than 1000 COVID-19 cases, have indicated that a reduced frequency of CD4+ T cells is related to disease severity." (PMID 36793739, 2023). "A large network of cells correlating with each other was increased in COVID-19, including groups of proliferating or activated CD4, CD8, Treg, B cells, plasma cells, NK (CD69+), and cMono." (PMID 36669118, 2023). "Eleven genes were upregulated in all groups, including TNF, and other effector molecules, including IFNG, GZMB, and PRF1, were upregulated after vaccination in spike-specific CD4+ T cells obtained from donors with a history of mild or severe COVID-19." (PMID 38064569, 2023). "Of note, it was also observed that low CD8+ T levels were more common than low CD4+ T levels in COVID-19 patients." (PMID 36986336, 2023).
COVID-19 (continued). "Our study concluded that the immune response to inactivated COVID-19 vaccination among PLWH was independently associated with CD4 cell count, PLWH with lower CD4 cell count showed a weaker humoral immune response, especially those with CD4 cell count < 200/μL." (PMID 36670363, 2023). "They observed a mortality of 26.1% among a cluster of patients with very high CD8+ and CD4+ activation in which 47.8% were patients with severe COVID-19." (PMID 36675642, 2023). "(C) Relative expression of IFNγ, IL-17A, TGFβ, and IL-10 genes in peripheral blood CD3+ CD4+ cells from COVID-19 patients (moderate or severe) and healthy control (HC)." (PMID 37523305, 2023). "Altogether, there were 348 CD4+ T-cell responses detected in 27 COVID-19 patients and 178 responses in 14 seronegative controls." (PMID 37215095, 2023). "SARS-CoV-2 infection induces vigorous CD4+ and CD8+ T cell responses against different viral antigens while CD4+ T cells are clearly important for the success of COVID-19 vaccines." (PMID 38006052, 2023). "Previous studies indicated that PLWH with a CD4 count of less than 200 cells/μl had significantly weakened immune responses to COVID-19 vaccine compared with healthy individuals." (PMID 37404815, 2023). "In the AID group, a slight increase in NK cell counts (p = 0.04) and proportions (p = 0.13) was observed after COVID-19 recovery, while the proportion of CD4+ T cells decreased significantly (p = 0.05)." (PMID 37893180, 2023). "Prior research has established that reduced CD4+/CD8 + T cells and lymphocyte count are associated with severe COVID-19 and mortality." (PMID 37932685, 2023). "SARS-CoV-2 maternal infections display higher frequencies of CXCR5+CD4+ and CCR6+CD4+ T cells and higher plasma concentrations of IL-6 and IL-18, when compared with gestational age–matched COVID-19–vaccinated counterparts." (PMID 37490342, 2023). "The finding that SARS-CoV-2 escaped the CD4+ clonotype with multiple potentials in the absence of humoral immunity further suggests a previously unclear role of CD4+ cells in the immune protection against COVID-19." (PMID 37124420, 2023). "A similar finding was discovered in China where COVID-19 patients with severe disease activity had a significant reduction of CD4+ and CD8+ cell count (p < 0.05) compared with patients’ with mild-moderate severity." (PMID 37377785, 2023). "First, we conducted Mendelian randomization (MR) of cis-eQTLs obtained from single-cell RNA-sequencing (scRNA-seq) data from CD4 + T-cell subtypes at varying times after stimulation with gene expression as exposures and COVID-19 severity as an outcome." (PMID 37640912, 2023). "The production of cytokines in COVID-19 patients and CD4+ T lymphocytes isolated from SARS-CoV-2-vaccinated subjects stimulated with a peptide pool predominantly expressed IL-2 and IFN-γ, whereas IL-17A, IL-4, and IL-10 were less frequent and not significant." (PMID 38140191, 2023). "In concordance, we also found an enriched ER stress response in activated CD4+ T cells in COVID-19 positive individuals." (PMID 37886355, 2023). "We showed that two doses of vaccines induced CD4+ and CD8+ responses in the majority of uninfected and post-COVID-19 individuals, but CD4+ and CD8+ responses in both groups subsequently declined to comparable levels after three months." (PMID 37112825, 2023). "This It is consistent with earlier published data that CD4 cells, alongside with various immune cells, can be altered in more severe cases of COVID-19 35, 41-42." (PMID 37057213, 2023). "Similar trend was observed with expression of RORγT in CD8+CD4- T cells, its percentage being highest in IV stage of COVID-19." (PMID 37057213, 2023). "S-peptide induced CD4+ T-cell proliferation to a higher extent in naïve than in subjects recovered from COVID-19 early after the second vaccination dose, with a similar trend in CD8+ T cells." (PMID 37153580, 2023).